IL6 (interleukin 6)
Diseases named in the same sentence as IL6 in open-access papers (continued):
Sharing a sentence is not in itself a finding about the gene and the disease.
tumor (continued). "Upon cancer development, IL-6 and IL-8 are secreted by tumor-infiltrating immune cells within the tumor microenvironment (TME)." (PMID 39136000, 2024). "Mesenchymal stem cells activate STAT3 in OS cells through secretion of IL-6, thereby increasing tumor growth and metastasis and decreasing apoptosis." (PMID 39199574, 2024). "Disruption of the intercellular circNOX4/IL-6 axis significantly suppressed tumor growth and metastatic colonization in vivo." (PMID 38459511, 2024). "Here, the mRNA levels of proinflammatory cytokines Tnfa, Il6, Il1b as well as the chemokine Ccl2 were significantly higher in Plg− tumors relative to Plg+ tumors consistent with the smaller tumor size and increased levels of apoptosis." (PMID 37971174, 2024). "Recent, in vivo evidence on GC showed that IL-6/STAT3 signaling can be activated in the tumor environment through persistent inflammation." (PMID 39456519, 2024). "The pro-inflammatory cytokine interleukin-6 (IL-6) has been extensively studied relative to other interleukins due to its multifaceted role in immune modulation and tumor progression." (PMID 39335733, 2024). "In turn, Jagged2 promotes tumor growth and therapeutic resistance by stimulating IL-6 release from mesothelial cells." (PMID 38575576, 2024). "miR-99a-5p plays an anti-tumor role in tumor metastasis by targeting CDC25A/IL6 to hinder the Epithelial–Mesenchymal Transition (EMT) process in human cervical squamous cell carcinoma." (PMID 37925811, 2024). "As observed in lymphocyte cultures, the cytokine IL-10 was differentially produced only in monocyte cultures with the empty vector and E5 transfected tumor cells, and IL-6 was highly produced in all experimental groups, especially when E7 was transfected." (PMID 38793599, 2024). "OSM/IL-6/JAK signaling has been reported to support tumor progression by promoting a CSC phenotype and epithelial-mesenchymal plasticity." (PMID 38236642, 2024). "Augmented IL-6 and IL-17, seen in 4THM tumor sera and in collagen gels, were thought to be a likely explanation for the increased 4THM tumor invasion, and indeed, the increase was abolished by anti-IL-6/IL-17 antibodies." (PMID 38540350, 2024). "This pathway triggered by intracellular IL-6 significantly contributes to cell-autonomous induction of senescence and impacts in tumor growth control." (PMID 39012326, 2024). "We also suggest that the uncontrolled expansion of this subset in double mutant mice derives from an exacerbation in the production of IL-6 cytokines by immature tumor T-cells." (PMID 39337370, 2024). "IL-6 promotes the formation of tumor blood vessels, accelerates tumor proliferation, and increases the ability of tumor cells to invade and metastasize." (PMID 39619013, 2024). "In CRC, exosomes from tumor cells, rich in circular RNAs, activate TAMs’ NF-κB pathway, leading to IL-6 secretion and triggering tumor cells’ Janus kinase 2 (Jak2)/STAT3 pathway." (PMID 39286635, 2024). "PD-L1 protein expression in tumor cells is upregulated by interleukin (IL)-1, IL-6, tumor necrosis factor-α (TNF-α), and interferon-γ (IFN-γ)." (PMID 38817669, 2024). "On the other hand, elevated STAT3 in the stromal cells of the host confers an immune-suppressed tumor microenvironment, with specific roles identified for IL-6 and IL-11." (PMID 39128004, 2024). "CAF also interfere with drug resistance by inducing and maintaining the stemness of the tumor, promoting increased efflux of chemotherapeutic drugs, and by secreting pro-inflammatory cytokine IL-6 that has been correlated with resistance to paclitaxel." (PMID 39513004, 2024). "Within the TME, activated M2b macrophages secrete IL-6, which in turn activates Th2 cells, culminating in the creation of a pro-inflammatory milieu conducive to tumor progression." (PMID 38341519, 2024). "One of the major cytokines involved in this inflammation is IL-1β, which promotes tumor growth and invasiveness through the stimulation of IL-6, TGFβ, and TNFα." (PMID 39394174, 2024).
tumor (continued). "IL-6, a well-established cytokine induced by IL-1β in intestinal epithelial cells (IECs), has been shown to promote tumor progression in CAC through the activation of the oncogene STAT3 in addition to IL-11." (PMID 38607004, 2024). "Cytokines like tumor necrosis factor alpha (TNF-α), TGF-β, IL-6, IL-10 and IL-17 secreted in either an autocrine, endocrine or paracrine manner have assumed a pivotal role in promoting tumor survival and metastasis." (PMID 38254117, 2024). "In the body, quercetin reduces the effects of inflammatory mediators and cytokines such as TNF-α, IL-6, thus exerting anti-inflammatory and anti-tumor effects." (PMID 39193369, 2024). "The activation of the IL-6 signaling pathway in HCC enhances tumor infiltration of Tregs that suppress cytotoxic CD8+ T cells, thereby promoting immune evasion and tumor progression." (PMID 38426090, 2024). "We further showed an increase in the infiltration of immune cell population in the IL-6 KO tumors compared with wild-type controls and the defective IL-6 KO tumor growth was rescued in immunodeficient mice while cachexia was not." (PMID 38671295, 2024). "In conclusion, our study demonstrates that ESP can effectively reduce IL-1β and IL-6 levels, suppress inflammation in RA, inhibit tumor-like proliferation of synovial cells, counteract NF-κB phosphorylation, and protect against joint damage in the RA model." (PMID 38846095, 2024). "Some cytological studies have shown that adipose-derived stem cells promote the proliferation and invasion ability of BCa cells by secreting proinflammatory cytokines such as IL-6 and IL-8, and play a positive role in tumor progression." (PMID 39668829, 2024). "Levels of IL-6 mRNA were found to be significantly (P < 0.05) upregulated in tumor bearing mice compared to control tumor-free mice." (PMID 39394174, 2024). "In the tumour microenvironment, the IL-6/STAT3 axis drives the proliferation, invasiveness, and metastasis of cancer cells, and strongly suppresses the antitumour immune response." (PMID 37950040, 2024). "The signal transduction facilitated by IL-6 plays a vital role in mediating interactions between tumor cells and stromal cells." (PMID 38828409, 2024). "The controlling role of myofibroblasts, particularly in producing IL-6, underscores their potential significance in the stromal desmoplasia of tumours." (PMID 39676864, 2024). "The IL-6 effects, which are beneficial during wound healing, are turned against the organism during tumorigenesis; hence, processes that occur during tumor development resemble those in wound healing." (PMID 38715108, 2024). "The primary tumor expression profiles of nine patients with high serum IL-6 levels and nine patients with low serum IL-6 levels were compared while ensuring that clinicopathological factors, such as primary site and stage, were similar." (PMID 38510850, 2024). "In summary, we have demonstrated that aberrantly activated mTORC1 contributes to ferroptosis resistance and tumor growth by regulating of the ERO1α/IL-6/STAT3/SLC7A11 signaling pathway." (PMID 38610018, 2024). "At the same time, induced release of MUC16c into the cytoplasm also promotes the secretion of IL-6, which activates the JAK2/STAT3 pathway, promotes the expression of Foxp3 in tumor tissues and the abundance of tumor-associated regulatory T cells (Tregs)." (PMID 38758220, 2024). "In orthotopic tumor mouse models, we observed suppression of HPV − tumors upon inhibition of IL6, accompanied by increased tumor infiltration and proliferation of CD161+ NK cells." (PMID 38468260, 2024). "In vivo results showed that after 20 days of gavage administration of SNLP‐1 (4 mg/kg/day), macrophages in the LLC tumor model mice significantly down‐regulated NO, TNF‐α, and IL‐6, reducing tumor volume and weight." (PMID 39155844, 2024). "Myeloid-derived growth factor promotes chemotaxis of macrophages into tumor tissues, enhancing their release of inflammatory cytokines such as IL-6 and TNF-α." (PMID 39068459, 2024).
tumor (continued). "Treatment of tumor stromal organoids in culture with docetaxel induces cytokine secretion (Csf3, Csf2, Il-6, Cxcl1, Cxcl2, and Tnfα) into the cell culture media while reducing levels of Vegf." (PMID 39338937, 2024). "Experimental administration of IL-6 inhibitors or receptor antagonists has been shown to reduce tumor growth increase the activity of cytotoxic T cells or natural killer cells in mouse models of PC." (PMID 38689325, 2024). "Mechanistically, senescent tumor cells derived IL-6 induces the upregulation of TAMs CD73 expression through JAK/STAT3 signaling pathway." (PMID 38323313, 2024). "It has been revealed that IL-6 trans-signaling via sIL-6R derived by myeloid cells attenuates CD4+ T helper type 1 (Th1) cell differentiation in tumor-bearing mice, leading to defective anti-tumor responses." (PMID 38182653, 2024). "IL-6 is a major regulator of myeloid-derived suppressor cells (MDSCs) that suppress the anti-tumour functions of T and NK-cells." (PMID 38468349, 2024). "A well-described mechanism is that during aging, hepatic stellate cells adopt aging-related changes and secrete various inflammatory and tumor-promoting factors, including IL-1β, IL-6 and CXCL7, to induce neutrophil infiltration." (PMID 38539791, 2024). "Both IL‐6/IL‐6R blockade and O‐glycan truncation in tumor cells induced similar pro‐inflammatory phenotypes in macrophages and cytotoxic T lymphocytes (CTLs)." (PMID 37452653, 2024). "TIM-3, a common co-inhibitory immune checkpoint in GBM, regulates GBM cell malignancy and induces macrophage migration and polarization toward an anti-inflammatory or pro-tumor phenotype through the IL-6 pathway." (PMID 38720342, 2024). "The tumor microenvironment, characterized by inflammatory cytokines such as IL-1 (Interleukin-1) and IL-6 (Interleukin-6), can modulate miRNA expression, thereby affecting PTEN levels." (PMID 39298504, 2024). "More importantly, tumor‐localized inflammation is concurrently reduced, as evidenced by decreased levels of pro‐inflammatory factors, including TNF‐α and IL‐6, in tumor tissues at the end of the therapeutic period." (PMID 38943265, 2024). "This involves the activation of genes that encode pro-inflammatory cytokines like tumor necrosis factor-alpha (TNF-α) and interleukin-6 (IL-6), which not only sustain inflammatory responses but also support tumor growth and survival." (PMID 38474160, 2024). "A similar mechanism has been observed in esophageal-induced tumor models, where P. gingivalis exhibits a tumorigenic effect by inducing inflammation through IL-6 interleukin secretion." (PMID 39336457, 2024). "The inflammatory tumor microenvironment is orchestrated by cytokines such as IL-6, IL-1β, TNF-α, and IL-23." (PMID 39766123, 2024). "NF-κB plays an important role in CAFs, mediating the upregulation of proteases such as COX2, CXCL1, CXCL2, CYR61/CCN1, IL-1β, IL-6, and osteopontin, thus promote tumor growth, recruit macrophages, and form tumor vasculature." (PMID 39146202, 2024). "STAT3/miRNA/IL-6 feedback loops promote tumor cell proliferation and epithelial–mesenchymal transition (EMT), and accelerate the development of various diseases, such as cervical squamous cell carcinoma (CSCC)." (PMID 38172648, 2024). "The conversion of WAT to brown adipose tissue (BAT) can be activated by inflammatory mediators such as IL-6, as well as tumor-driven molecules like parathyroid hormone-related protein (PTHRP)." (PMID 38791998, 2024). "In this study, we performed a microarray analysis of tumor tissues with high and low serum IL-6 levels." (PMID 38510850, 2024). "Consistent with earlier research, these findings show that IL-6 regulates tumor formation and glucose metabolism via the IL-6R/STAT3 axis." (PMID 39060229, 2024). "IL-6 levels have been shown to increase with tumor stage and during lung cancer progression, and have been associated with poor survival." (PMID 38339362, 2024).
tumor (continued). "TANs 2 also regulate tumor growth via the IL-6/STAT3 axis and proangiogenic as well as metastatic markers, such as VEGF and MMP9." (PMID 39335210, 2024). "IL-6 levels have been shown to be elevated within the tumour micro-environment (TME) of DLBCL, where it is produced by reactive immune and stromal cells (particularly macrophages and endothelial cells), as well as by the tumour cells directly." (PMID 38633747, 2024). "IL-6, IL-10, and IL-4 are considered the main Th2 immune cytokines, mainly encouraging tumor growth by hindering the host’s immune system." (PMID 38361933, 2024). "The pro-tumoral activities of IL-6 are related to its ability to directly act on tumor cells by activating STAT3, which in turn promotes their proliferation, survival, and invasive potential." (PMID 39281678, 2024). "It is highly binding to IL-6, leading to the neutralization of IL-6 bioactivity and the induction of tumor cell death." (PMID 39125732, 2024). "Although a minor contributor within the OC-TME, endothelial cells can also produce IL6 in response to hypoxia or signals from tumor cells." (PMID 39766086, 2024). "The mechanisms underlying OIIA-LPD include suppression of tumor immunity, activation of B cells resulting from Epstein-Barr virus (EBV) infection, and IL-6 activation." (PMID 39569043, 2024). "Specifically, neutrophils in NSCLC secrete IL-6 and IL-12, fostering the tumor’s inflammatory microenvironment." (PMID 38966070, 2024). "First, IL-6 facilitates tumor cell proliferation and survival by activating signaling pathways that promote cell growth and impede apoptosis." (PMID 38534979, 2024). "NFκB facilitates tumor cell survival, proliferation, and angiogenesis by regulating the expression of target genes such as cyclin D1, IL6, BCLXL, BCL2, XIAP, and VEGF." (PMID 39203892, 2024). "Consistently, IL-6 staining in tumor sections from the EGC reporter mouse line Sox10CreERT2Ai14fl/fl, revealed that IL-6 protein co-localized with tdTomato+ cells in AOM/DSS tumors." (PMID 39030280, 2024). "IL-6 regulates tumour proliferation and differentiation mainly by mediating the IL-6/STAT3 signaling pathway." (PMID 38613794, 2024). "When the level of IL‐6 in peripheral blood and tumour homogenates was assessed using ELISA, we found that calycosin downregulated IL‐6 production." (PMID 37974543, 2024). "Suppressing IL-6 levels results in decreased PD-L1 expression within the tumor microenvironment, leading to diminished tumor growth and enhanced survival outcomes." (PMID 39690423, 2024). "It is worth mentioning that besides an IL‐6/JAK2/STAT3 axis‐dependent induction of a macrophage‐tumor cell crosstalk our study uncovered an EV‐mediated crosstalk between tumor cells and macrophages." (PMID 38031260, 2024). "In our TAME system, when CAFs were exposed to BCa cell-secreted GM-CSF, they subsequently upregulated the inflammation-associated genes IL-6, IL-6R, IL-8 and CXCL3, which support both tumor progression and CAF survival." (PMID 39199680, 2024). "This decrease in IL-6 promotes M1 macrophage polarization, restores their phagocytic capacity, and alleviates the inhibitory effects of IL-6 on tumor cell apoptosis, thereby enhancing anti-tumor activity." (PMID 39575419, 2024). "Regarding tumor promotion, IL-17 secreted by Th17 cells can stimulate TCs through the IL-6/Stat3 signaling pathway, promoting their proliferation, migration, and invasion." (PMID 38755133, 2024). "IL-6 is generated by several cells present inside the tumor, such as tumor-infiltrating cells and stromal cells." (PMID 38279309, 2024). "Interleukin-6 (IL-6), an inflammatory cytokine, is frequently accumulated in the tumor microenvironment." (PMID 39796677, 2024).
tumor (continued). "After postoperative tumor resection, plasma IL-6 was still induced prominently in the IgG2b, κ group." (PMID 38505617, 2024). "O‐glycan truncation in tumor cells suppressed IL‐6 expression and induced pro‐inflammatory phenotypes in macrophages and CTLs." (PMID 37452653, 2024). "This, in turn, stimulated the expression of IL-6 in both tumor and stromal cells, establishing an inflammatory microenvironment that promotes tumor growth." (PMID 38709264, 2024). "Cancer-associated fibroblasts are themselves known to be a rich source of exosomal miRNAs, and can alter the expression of a number of molecules, including IL-6 and those of the Wnt pathway, which can contribute to tumor invasion." (PMID 38540350, 2024). "Conversely, IL‐6 and IL‐1β protein levels were elevated in the tumour tissues of GV493‐RNAi cell xenotransplanted nude mice models." (PMID 39495702, 2024). "Immunohistochemical staining of tumor tissue indicated that DI/Pep1 reduced the expression of the inflammatory factor IL‐6." (PMID 39545088, 2024). "In these diseases, higher IL-6 levels are correlated with more advanced disease stage, increased tumor aggressiveness, and worse clinical outcomes." (PMID 38689325, 2024). "Secondly, they found that the high-level α-SMA CAFs expressed low-levels of IL6 and were only activated when tumor cells came into direct contact with PSCs." (PMID 38540204, 2024). "Circulating tumour cells (CTCs) and interleukin-1β (IL-1β), interleukin-6 (IL-6), interleukin-8 (IL-8), and interleukin-10 (IL-10) were measured in a pilot group of 40 patients at baseline and before cycle two (C2) and cycle three (C3)." (PMID 38398148, 2024). "Notch-mediated autocrine secretion of IL-6 in MM cells allows for increased independence from the tumor microenvironment (TME) for MM cell survival." (PMID 39619207, 2024). "Myeloid-derived suppressor cells (MDSCs) can activate the Notch signaling in tumor cells through the secretion of interleukin-6 (IL-6), and the activation of Notch in tumor cells can impact the recruitment of immune cells." (PMID 39343952, 2024). "These Exos harbor FGD5-AS1 and IL-6 with the potential to increase tumor cell metastasis and survival via the promotion of M2 TAMs via the STAT3/NF-κB pathway." (PMID 38360641, 2024). "IL-6 in one of the key cytokines produced by normal cells during inflammation; besides, IL-6 is one of the most important cytokines in the tumor microenvironment - its protumor and anti-tumor effects are well known and extensively described in the literature." (PMID 39206193, 2024). "We show that BCG induced the recruitment and polarization of macrophages towards a pro-inflammatory phenotype, accompanied by induction of the inflammatory cytokines tnfa, il1b and il6 in the tumor microenvironment." (PMID 39114912, 2024). "This study confirms that IL-6 within the tumor microenvironment plays a crucial role in the intercellular communication." (PMID 38422751, 2024). "One study reported that in obese Pten-knockout mice, HFD was associated with increased tumor growth and inflammatory cells associated with the TME including an increased M2:M1-type macrophage ratio, IL-6 and myeloid-derived suppressor cells." (PMID 39840030, 2024). "Characteristically, M1 macrophages release pro-inflammatory agents like TNF, IL-1, IL-6, and IL-12, which possess tumor-fighting properties." (PMID 39702158, 2024). "MCT-1 induces angiogenesis and tumor evasion from immune surveillance by stimulating interleukin 6 (IL-6) secretion, and downregulation of its expression suppresses M2 macrophage polarization and increases M1 macrophage polarization." (PMID 38523627, 2024). "Interleukin 6 (IL-6) is a proinflammatory cytokine and has been found to regulate growth in malignant tumor cells." (PMID 38254757, 2024). "Other mechanisms for the protumorigenic effect of IL-6 include the suppression of tumor senescence, the interaction with growth factor signaling, the induction of EMT, and angiogenesis." (PMID 38520006, 2024).